MTOR (mechanistic target of rapamycin kinase)
Diseases named in the same sentence as MTOR in open-access papers (continued):
Sharing a sentence is not in itself a finding about the gene and the disease.
pancreatic cancer (continued). "In one study on patients with pancreatic cancer and weight loss, decreased protein levels and activation of Akt, mTOR, p70S6K, GSK3-ß and FoxO1 were observed in skeletal muscle tissue compared to samples from patients with pancreatic cancer without weight loss." (PMID 26856534, 2016). "Besides, mTOR inhibition could suppress the expression of VEGF-C and effectively reduce lymphangiogenesis in pancreatic cancer mouse model." (PMID 25884175, 2015). "The absence of 4E-BP1 and 4E-BP2 in pancreatic cancer cells prevents G1 phase inhibition by mTOR inhibitors owing to a less effective repression of general protein synthesis and, more specifically, to a lack in the repression of cyclin D1 post-transcriptional expression." (PMID 25594050, 2014). "Here we verify in four distinct primary pancreatic cancer cell lines derived from patient tumors that cancer stem cell-enriched sphere cultures indeed show marked overexpression of SHH and the Hedgehog target genes GLI-1 and GLI-2, as well as increased mTOR pathway activity." (PMID 23825539, 2013). "Therefore inhibiting mTOR activity by AZD8055 may be an effective way to overcome radioresistance and potently sensitize pancreatic cancers to radiation." (PMID 23886294, 2013). "In the K-ras wild-type pancreatic cancer cases, although in less than 10% of the cases, the mTOR inhibitors may have potential therapeutic importance since they often harbor RAS-MAPK pathway-activating alterations and elevated phosphorylation mTOR pathway proteins." (PMID 35039004, 2022). "Although it is contradictory that mTOR plays negative roles in autophagy, it shows the collaborate of mTOR and autophagy mediated by STYK1 at least in the cases of EGFR-TKIs resistance or pancreatic cancer with activating KRAS mutations and high basal autophagy." (PMID 37192859, 2022). "Hence, we treated pancreatic cancer cells with RSL3 (a well-known ferroptosis inducer that inhibits GPX4) in the presence of Wortmannin (WM, a well-known autophagosome inhibitor that supresses autophagosome) or Rapamycin (RA, a well-known autophagy activator that inhibits mTOR)." (PMID 36248959, 2022). "While KLT alone cannot cure lethal human malignancies such as pancreatic cancer, there are no previous findings on the effect of KLT on the PI3K/Akt/mTOR pathway in treating pancreatic cancer." (PMID 25005526, 2014). "Additionally, it was noticed that the total mTOR did not change; however, the p-mTOR and PI3K decreased significantly, demonstrating that the PI3K/AKT/mTOR cascade participates in the inhibition of pancreatic cancer (PANC-1) cells induced by fisetin." (PMID 36558146, 2022). "Besides, we determined the possible mechanism of repression by fisetin in pancreatic cancer and discovered that fisetin triggers apoptosis by specifically via targeting PI3K/AKT/mTOR cascade rather than JAK2 signaling." (PMID 34821587, 2021). "Particular attention was paid to MEK/ERK and AKT/MTOR, which are the two main signaling pathways responsible not only for cell growth deregulation and survival, but also for EMT induction and for the modulation of autophagy in pancreatic cancer cells." (PMID 34638477, 2021).
Obesity (532 papers, 2008 to 2026). Accumulation of substantial excess body fat. "Vitamin D’s ability to suppress mTOR activity helps prevent excessive fat accumulation and lowers the risk of obesity and its associated metabolic disorders." (PMID 40076782, 2025). "These epigenetic changes can stably activate or silence key genes within the AMPK/mTOR and PPARγ/C/EBPα networks over the long term, thereby providing a molecular “memory” that influences susceptibility to obesity and metabolic diseases." (PMID 41488302, 2025). "Leptin regulates immune cell function changes associated with obesity via mTOR regulation, which regulates protein synthesis, ribosome biogenesis, and autophagy, modulating proinflammatory immune cell functions." (PMID 40696355, 2025). "The mTOR signaling pathway is known for its role in obesity, a risk factor for diabetes, which also influences embryonic growth." (PMID 40362828, 2025). "The bidirectional communication between estrogen receptors and mTOR is a core mechanism in obesity-associated endometrial pathology." (PMID 41301707, 2025). "Leptin, an important adipokine, acts on molecular pathways such as PI3K/AKT and mTOR is encoded by the obesity gene and is involved in the process of regulating food intake." (PMID 40717997, 2025). "Recent research has demonstrated that several adipokines that are dysregulated in obesity can cause heterotopic ossification in tendons via the mTOR (mechanistic target of rapamycin) pathway." (PMID 41007814, 2025). "Another study showed that rapamycin alleviates age-dependent obesity, which is associated with increased mTOR signaling in hypothalamic POMC neurons." (PMID 40299431, 2025). "A recent study demonstrates that obesity can induce the expression of PD-1 on tumor-associated macrophages, which is mediated by the activation of mechanistic target of rapamycin (mTOR) and MYC (MYC proto-oncogene, bHLH transcription factor)." (PMID 40863244, 2025). "It has been reported that the PI3K/Akt/mTOR cascade is a target of many obesity-associated factors that regulate cell proliferation and survival." (PMID 40768543, 2025). "Instead, both miR-100 and miR-197 are associated with obesity, but a high level of miR-100 correlates with the block of cell cycle progression by inhibiting the mTOR pathway, thus leading to stemness maintenance at the expense of adipocyte commitment." (PMID 38921832, 2024). "Disruptions in energy sensors, such as inhibition of AMP-activated protein kinase (AMPK) and activation of the mammalian target of rapamycin (mTOR) in the hypothalamus, have been associated with both obesity and early onset of puberty." (PMID 38535297, 2024). "Dysregulation in mTOR signaling is associated with several conditions including obesity, type 2 diabetes, cancer, and aging." (PMID 38786985, 2024). "By modulating key regulatory pathways such as sirtuins, PGC-1α, IIS, PI3K/Akt, FOXO, and mTOR, IF can help prevent the premature aging associated with obesity." (PMID 39044934, 2024). "This activation triggers the kinase AKT, which, in turn activates mammalian target of rapamycin (mTOR), a key downstream target closely associated with the pathogenesis of obesity." (PMID 39264906, 2024). "Prolonged mTOR activation has indeed been shown to induce the conversion of brown adipocytes into a “white” state, which is linked to metabolic disturbances and obesity." (PMID 39256343, 2024). "Obesity is associated with the induced mTOR pathway, which is implicated in many comorbidities, including NAFLD." (PMID 36838721, 2023). "It has been discovered that at least some parts of insulin resistance induced by obesity were caused by p66Shc and mTOR pathways." (PMID 36465704, 2022). "Previously, we showed that Dicer1 deletion-associated hyperphagic obesity is strongly dependent on over-activation of the PI3K-Akt-mTOR pathway." (PMID 35490865, 2022).
Obesity (continued). "This study identified upregulated neural mTOR signaling through TSC2 knockout as a key mechanism that predisposes to the HFD-associated onset of normal weight obesity." (PMID 36586433, 2022). "It was documented that obesity in pregnancy is linked to stimulation of placental insulin/IGF-1/mTOR and leptin signalling pathways." (PMID 35884994, 2022). "In mice, POMCCre-dependent over-activation of the phosphatidylinositol-3-kinase (PI3K)-Akt-mammalian target of rapamycin (mTOR) pathway causes hyperpolarization of POMC neurons leading to obesity." (PMID 35490865, 2022). "The objective of this study was to isolate the role of constitutive mTOR activation in Nav1.8-expressing peripheral neurons in the onset of diet-induced obesity, bone loss, and metabolic disease." (PMID 36586433, 2022). "Of note, hyperactivation of mTOR signaling has been observed in experimental models of endometrial cancer associated with obesity and in a large fraction of endometrial tissues from obese endometrial cancer patients, compared with non-obese patients." (PMID 35053431, 2022). "The agent metformin, an inhibitor of mTOR activity, can prevent such processes during obesity in experimental mouse models and can reverse the loss of SIRT1 function during inhibition of the circadian components CLOCK and BMAL1." (PMID 34590471, 2021). "These pathologies, which are strikingly similar to age- and obesity-associated human diseases, were partially prevented by mTOR inhibition through AICAR, metformin or rapamycin." (PMID 34572128, 2021). "A report demonstrated that weight loss critically regulates the mTOR/p70S6k pathway by promoting protein synthesis in rat models with obesity." (PMID 34233719, 2021). "mTOR is a master regulator of cellular growth and metabolic activity, and its hyperactivation has been linked to obesity and type 2 diabetes." (PMID 33922377, 2021). "Obesity, a known risk factor for COVID-19, stimulates chronic hyperactivation of mTOR activity in multiple tissues." (PMID 33491531, 2021). "Because obesity is caused by excessive energy intake over time, can the energy sensor mTOR affect the mitochondrial quality control of brown adipocytes and thus regulate the “whitening” of brown adipocytes?" (PMID 34335285, 2021). "Dysregulation of the mammalian target of rapamycin (mTOR) signalling pathway is also implicated in obesity." (PMID 32191726, 2020). "The mechanistic/mammalian target of rapamycin (mTOR) is widely implicated in the pathogenesis of various diseases, including cancer, obesity, and cardiovascular disease." (PMID 31263418, 2019). "Given the effects of high dose tamoxifen upon PKC mitogenic signals, PKCζ must be considered a top candidate, as PKCζ signals are involved in obesity associated β-cell proliferation via mTOR and Cyclin-D2." (PMID 31490929, 2019). "We believe that clarifying the roles and underlying mechanisms of mTOR-related signaling in adipocytes will provide potential therapeutic targets for obesity and related metabolic disorders." (PMID 31708995, 2019). "Although global deletion of mTOR, Raptor, and Rictor results in embryonic lethality, cell-specific deletion strategies show that mTOR is implicated in the pathogenesis of various diseases, including cancer, obesity, and cardiovascular disease." (PMID 31263418, 2019). "Using the inhibitors of MAPK/ERK, U0126, we found that the crosstalk among the signaling pathways of MAPK/ERK, Akt-mTOR, and the inflammatory adipogenesis can be the possible mechanism of salt-linked obesity." (PMID 30621146, 2019). "Dysregulation in mTOR signaling is associated with various diseases such as obesity, type 2 diabetes, cancer, and neurological diseases." (PMID 30011848, 2018). "The mTOR signaling pathways are essential for cell growth and clinically mis-regulation of the mTOR pathways are implicated in human diseases including tumor formation, obesity, epilepsy, autism and neurodegeneration." (PMID 30080879, 2018).
Obesity (continued). "Given the critical role of GSK3β, the direct substrate of CCRK24 on mTOR signaling in obesity-associated HCC20,22, it is conceivable that the CCRK/GSK3β cascade regulates mTORC1 signaling to promote obesity-associated hepatocarcinogenesis." (PMID 30523261, 2018). "Persistent activation of mTOR is related to cancer, diminished cardiac performance and obesity associated metabolic diseases and has been associated with a significant reduction in autophagy." (PMID 30271655, 2018). "Dysregulation in mTOR signalling is implicated in various diseases such as obesity, T2DM, cancer and ageing." (PMID 28643459, 2017). "Conversely, genetic ablation of Sestrin2 augments mTOR activation and aggravates obesity-associated features such as glucose intolerance, insulin resistance, and hepatosteatosis in mice." (PMID 28690762, 2017). "Upregulation of mTOR associates with various pathological conditions, such as obesity, neurodegeneration, and brain tumors." (PMID 29259984, 2017). "Increased activation of the PI3K/AKT/mTOR signaling pathway as a central regulator of proliferation and metabolism has been implicated in diabetes, obesity and cancer." (PMID 26959121, 2016). "Mechanistic target of rapamycin (mTOR) signaling pathway is associated with metabolic disorders such as obesity and type 2 diabetes (T2D)." (PMID 27471110, 2016). "In order to explore possible mechanism underlying inhibition of placental mTOR signaling in obesity, we examined the activation of energy, insulin, and inflammatory pathways, which are upstream modulators of mTOR." (PMID 24744907, 2014). "In recent studies, a link between obesity, diabetes and breast cancer has been made through insulin/insulin-like growth factor and PI3K/Akt/mTOR signaling pathways and through obesity-induced chronic inflammation caused by adipose tissue dysfunction." (PMID 24978626, 2014). "We believe that a better understanding of the interrelationship between SIRT1 and mTOR signaling will promote the development of new pharmacological insights to treat metabolic diseases associated with obesity." (PMID 25330910, 2014). "This conjecture, as well as the proposed importance of the PI3K/Akt/mTOR pathway in mediating the effects of obesity-associated systemic factors, is supported by the literature on endocrine resistance." (PMID 23880059, 2013). "Deregulation of mTOR activity is linked to a variety of human diseases including cancer, obesity, type 2 diabetes, and neurodegeneration." (PMID 24069341, 2013). "mTOR signaling plays an important role in cellular metabolism and has been linked to obesity and diabetes." (PMID 23682635, 2013). "Several studies have linked the AKT/PI3K/mTOR pathway to obesity and, independently, the circadian rhythm to metabolic syndrome." (PMID 19203388, 2009). "For instance, studies by Jansson & Powell showed that maternal undernutrition or obesity alters placental mTOR signaling and amino acid transport, predisposing to fetal growth restriction or overgrowth via dysregulated nutrient sensing and NF κB pathway activation." (PMID 40871618, 2025). "In addition, miR-103 hyperexpression is known to inhibit the phosphatidylinositol-3 kinase/rapamycin target signaling pathway in mammals (PI3K)/AKT/mTOR), which leads to appetite suppression and a reduced risk of obesity due to hyperphagia." (PMID 40217882, 2025). "In addition, pharmacological inhibition of the mechanistic target of rapamycin (mTOR) by rapamycin ameliorates age-dependent obesity phenotypes associated with dysregulated mTOR complex 1 (mTORC1) signaling in POMC neurons." (PMID 41037185, 2025). "miR-200a-3p and miR-200b-3p/PI3K/AKT/mTOR pathway may be an important mediator of obesity-associated metabolic homeostasis, and could serve as targeted therapy strategy for obesity." (PMID 40016734, 2025). "Indeed, others have also implicated disruption of mTOR and Wnt signaling in obesity and neurogenerative diseases." (PMID 41310161, 2025).
Obesity (continued). "Induction of mTOR in AT is associated with adipocyte hypertrophy, but its inhibition results in a decrease in the size and number of adipose cells, resulting in probable protection against obesity." (PMID 41287647, 2025). "Therefore, persistent mTOR activity has been connected to aging, inflammation, and carcinogenesis; all those conditions have also been linked to obesity." (PMID 39484291, 2024). "In addition to the MAPK and NF-κB pathways, the AMP-activated protein kinase (AMPK) and mTOR signaling pathways are intricately linked to the development and regulation of obesity, making them potential targets for therapeutic intervention." (PMID 38495901, 2024). "Studies have shown that obesity-induced autophagy inhibition in PTECs in type 2 diabetes patients and mice is associated with mTOR activation, and that the mTOR inhibitor rapamycin significantly improves renal autophagy deficiency in obese mice induced by a high fat diet." (PMID 36942026, 2023). "Since obesity can cause and exacerbate male-factor infertility by several means, the change of mTOR pathway in our study might affect male reproductive system, which needs further research." (PMID 35135573, 2022). "Neuronal architecture in the hypothalamus, involving neuropeptide Y (NPY) fibres and expression of neuropeptides and factors of the mTOR signalling pathway, takes part in the mechanisms protecting the males and predisposing Leu-females to obesity under the appropriate environment." (PMID 35806240, 2022). "In addition to controlling organismal growth and homeostasis, the mTOR signaling pathway has been linked to an increasing variety of clinical diseases, including obesity." (PMID 36501200, 2022). "However, the vast majority of POMCCreGFP + cells continue expressing POMC throughout the adulthood and the obesity phenotypes associated with POMCCre-restricted PI3K-Akt-mTOR pathway over-activation are largely explained by inactivation of POMC neurons." (PMID 35490865, 2022). "Interestingly, the mTOR signaling pathway is a regulator of several cellular processes including autophagy, and is implicated in different disorders including cancer and obesity." (PMID 35409166, 2022). "Interestingly, during obesity defective mTOR is observed in NK cells and mucosal-associated invariant T (MAIT) cells: O’Brien and colleagues described an inhibition of mTORC1 in MAIT cells dysregulating their cytokine profile during obesity." (PMID 35844529, 2022). "In the pilot study, we found that the crosstalk among the signaling pathways of MAPK/ERK, Akt-mTOR, and the inflammatory adipogenesis could be the possible mechanism of salt-linked obesity, similarly to in other studies." (PMID 34064531, 2021). "Hence; it has been suggested that targeting the mTOR pathway carries a potential for obesity treatment, thus mitigating the risk of COVID-19." (PMID 33491531, 2021). "With loss or gain of mTOR functional studies, we show that placental mTORC1 plays a major role in fetal programming of metabolic responses in the adult offspring, thereby contributing to susceptibility risk for obesity and T2D." (PMID 34032632, 2021). "Moreover, single nucleotide polymorphism analysis has revealed that a common genetic variation in regulatory-associated protein of mTOR (RAPTOR) is associated with overweight/obesity in American men of Japanese ancestry." (PMID 32191726, 2020). "This study highlights new regulatory mechanism by which serine tailors the immune responses of macrophages, implicating serine metabolism, and mTOR signaling as potential therapeutic targets for macrophage-associated diseases (e.g., cancer, obesity, and pathogen infection)." (PMID 32973770, 2020). "Because the influence of obesity may differ between the ER+ and ER− subtypes of breast cancer, we also examined the mTOR-body fatness associations stratified by ER status." (PMID 33024820, 2020).